C1orf198 (chromosome 1 open reading frame 198)
Synonyms: FLJ14525; MGC10710; FLJ16283; DKFZp667D152; FLJ38847
Tractability: PROTAC: ubiquitination databases record sites on it.
Gene: Protein-coding gene on chromosome 1 (230,837,119 to 230,869,589, reverse strand). Ensembl gene ENSG00000119280.
Subcellular location: Cytoplasm
Subcellular location (Human Protein Atlas): Cytosol
Gene Ontology:
Cellular component: cytosol; cytoplasm
Genetic constraint (gnomAD): Loss-of-function variants: 17 observed, 26.82 expected, observed/expected ratio (o/e) 0.63, 90% interval 0.43 to 0.95. The upper end of that interval is the gene's LOEUF score, 0.95, which puts it in group 4 of 6, group 1 being the genes least tolerant of losing a copy. Missense variants: 401 observed, 413.81 expected, observed/expected ratio (o/e) 0.97, 90% interval 0.89 to 1.05. Synonymous variants: 175 observed, 180.61 expected, observed/expected ratio (o/e) 0.97, 90% interval 0.86 to 1.1.
Homologues: Orthologues: chimpanzee C1H1orf198 (99% identical), dog C4H1orf198 (85% identical), rabbit C1orf198 (83% identical), mouse 2310022B05Rik (78% identical), rat C19h1orf198 (78% identical), pig C1orf198 (77% identical), guinea pig C1orf198 (77% identical), macaque C1H1orf198 (69% identical), tropical clawed frog c10h1orf198 (51% identical), zebrafish C20H1orf198 (41% identical), tropical clawed frog c5h1orf198 (35% identical).
Diseases named in the same sentence as C1orf198 in open-access papers:
C1orf198 is named in the same sentence as 5 diseases in open-access papers, as found by Europe PMC text mining. Sharing a sentence is not in itself a finding about the gene and the disease. The quoted sentences say what the papers report.
breast carcinoma (1 paper, 2025). "Previous studies have suggested that C1orf198 plays a role in the initiation and progression of gastric and breast cancers, but its relationship with CRC remains unclear." (PMID 41142306, 2025). "Previous studies have shown that C1orf198 plays a role in the development and progression of gastric and breast cancers, but its relationship with CRC remains unclear." (PMID 41142306, 2025).
pancreatic cancer (1 paper, 2017). "In previous study, C1orf198 was identified as novel gene in colon, gastric and pancreatic cancer, however, the GO functions of this gene were unknown yet." (PMID 29088749, 2017).
cancer (2 papers, 2023 to 2025). A tumor composed of atypical neoplastic, often pleomorphic cells that invade other tissues. "Using TCGA data, comparative analysis of C1orf198 mRNA expression in pan-cancer and normal tissues revealed expression differences across multiple cancer types." (PMID 41142306, 2025). "Given the potential of cancer cells to modulate immune cell polarization via chemokines and their receptors, this study investigated the relationship between C1orf198 expression and chemokine/receptor profiles sourced from the TISIDB database." (PMID 41142306, 2025). "The mRNA and protein expression levels of C1orf198 were analyzed in pan-cancer and CRC tissues." (PMID 41142306, 2025). "Another subgroup of PPIs presumably perturbed by cancers is characterized by negative or near-zero r-values in cancers and positive r-values of gene co-expression in conditionally normal tissues, for example, C1orf131/EIF3L, C19orf53/APEX1, C1orf198/PPP2R1A and C1orf198/ARHGEF1." (PMID 37373333, 2023).
tumor (1 paper, 2025). "This association implies a potential mechanism by which C1orf198 facilitates tumor immune escape: upregulated PD-L1/PD-1 signaling dampens cytotoxic T-cell responses, allowing tumors to evade immune surveillance." (PMID 41142306, 2025). "High C1orf198 expression correlated with advanced tumor stages (T, N, M) and poor survival outcomes, including shorter overall survival (OS), disease-specific survival (DSS), and progression-free interval (PFI)." (PMID 41142306, 2025). "These interactions likely drive a feedforward loop where C1orf198 upregulates chemokine signaling, attracting immunosuppressive cells while repelling cytotoxic T cells, thereby fostering a pro-tumor microenvironment." (PMID 41142306, 2025). "This outcome implies that C1orf198 has potential as a diagnostic biomarker for CRC, capable of partially differentiating tumor-bearing states from normal conditions." (PMID 41142306, 2025). "In conclusion, this study identifies C1orf198 as a potential prognostic biomarker in CRC, associated with tumor progression, ECM remodeling, and immunosuppressive TME formation." (PMID 41142306, 2025). "Immune infiltration analysis showed positive correlations with stromal/immune scores and M2 macrophage infiltration, linking C1orf198 to tumor microenvironment (TME) remodeling." (PMID 41142306, 2025). "These associations suggest that C1orf198 may interact with M2 macrophage-driven pathways to influence CRC progression and tumor-immune crosstalk." (PMID 41142306, 2025). "The enrichment of C1orf198 in M2-related pathways suggests it may drive macrophage polarization toward an immunosuppressive phenotype, creating a niche conducive to tumor progression and resistance to immunotherapy." (PMID 41142306, 2025). "In summary, C1orf198 emerges as a pivotal node in TME biology, integrating ECM remodeling, immune cell recruitment, and checkpoint signaling to promote a pro-tumor microenvironment." (PMID 41142306, 2025). "Collectively, these results suggest that C1orf198 may influence immune-cell-related processes in CRC, potentially impacting tumor-immune interactions." (PMID 41142306, 2025).
C1orf198 also shares sentences with these, for which no sentence is quoted: colorectal cancer (1 paper).